HES5 (hes family bHLH transcription factor 5)
Description:
Transcriptional repressor of genes that require a bHLH protein for their transcription. Plays an important role as neurogenesis negative regulator (By similarity).
Synonyms: bHLHb38
Tractability: PROTAC: ubiquitination databases record sites on it.
Gene: Protein-coding gene on chromosome 1 (2,528,745 to 2,530,263, reverse strand). Ensembl gene ENSG00000197921.
Subcellular location: Nucleus
Subcellular location (Human Protein Atlas): Nucleoplasm; Cytosol; Nuclear speckles
Pathways (Reactome):
Signal Transduction: NOTCH1 Intracellular Domain Regulates Transcription; NOTCH2 intracellular domain regulates transcription; NOTCH3 Intracellular Domain Regulates Transcription; NOTCH4 Intracellular Domain Regulates Transcription
Disease: Constitutive Signaling by NOTCH1 HD+PEST Domain Mutants; Constitutive Signaling by NOTCH1 PEST Domain Mutants
Gene Ontology:
Molecular function: sequence-specific double-stranded DNA binding; DNA-binding transcription factor activity, RNA polymerase II-specific; DNA-binding transcription repressor activity, RNA polymerase II-specific; RNA polymerase II cis-regulatory region sequence-specific DNA binding; DNA binding; protein dimerization activity
Biological process: cartilage development; negative regulation of stem cell differentiation; neuronal stem cell population maintenance; Notch signaling pathway; positive regulation of cell population proliferation; positive regulation of smooth muscle cell proliferation; anterior/posterior pattern specification; astrocyte differentiation; brain development; camera-type eye development; cell adhesion; cell maturation; central nervous system myelination; chondrocyte differentiation; glial cell fate commitment; negative regulation of astrocyte differentiation; negative regulation of neuron differentiation; negative regulation of oligodendrocyte differentiation; negative regulation of pro-B cell differentiation; negative regulation of transcription by RNA polymerase II; neural tube development; neuron differentiation; oligodendrocyte development; positive regulation of BMP signaling pathway; positive regulation of DNA-templated transcription; and 18 more
Cellular component: chromatin; nucleoplasm; nucleus
Genetic constraint (gnomAD): Loss-of-function variants: 12 observed, 8.04 expected, observed/expected ratio (o/e) 1.49, 90% interval 0.93 to 1.93. That is too few expected variants to judge how well the gene tolerates losing a copy. Missense variants: 223 observed, 136.63 expected, observed/expected ratio (o/e) 1.63, 90% interval 1.46 to 1.82. Synonymous variants: 115 observed, 69.2 expected, observed/expected ratio (o/e) 1.66, 90% interval 1.43 to 1.91.
Homologues: Orthologues: chimpanzee HES5 (99% identical), macaque HES5 (99% identical), pig HES5 (93% identical), mouse Hes5 (91% identical), dog HES5 (88% identical), guinea pig HES5 (86% identical), rat Hes5 (80% identical), zebrafish her4.2 (37% identical), zebrafish her4.5 (37% identical), zebrafish her4.1 (36% identical), zebrafish her4.3 (36% identical), zebrafish her4.4 (36% identical), and 14 more. Paralogues in human: HES1 (33% identical), HES4 (32% identical), HES2 (31% identical), BHLHE40 (30% identical), HES7 (30% identical), BHLHE41 (28% identical), HES6 (28% identical), HEY1 (28% identical), HEY2 (27% identical), HEYL (27% identical), HES3 (23% identical), HELT (21% identical).
Diseases named in the same sentence as HES5 in open-access papers:
HES5 is named in the same sentence as 74 diseases in open-access papers, as found by Europe PMC text mining. Sharing a sentence is not in itself a finding about the gene and the disease. The quoted sentences say what the papers report.
breast carcinoma (5 papers, 2009 to 2025). "We again found that HES5 significantly enriched the CSCs population and mammosphere forming ability in the primary breast cancer cells." (PMID 23495140, 2013). "The method was demonstrated on a tissue microarray dataset of 43 breast cancer patients, comprising approximately 40,000 imaged nuclei in which the HES5 and FRA2 genes were labeled with FISH probes." (PMID 22971117, 2012). "We detected the presence of active, cleaved Notch1, along with downstream targets of the Notch pathway, Hes1/Hes5, in ~75% of breast cancers, clearly indicating that in a large proportion of breast cancers Notch signaling is aberrantly activated." (PMID 20030805, 2009). "Interestingly, a specimen of breast epithelial hyperplasia also showed cleaved Notch1 and Hes5 positivity, indicating that Notch signaling might be activated at a very early stage of breast cancer progression." (PMID 20030805, 2009). "Increasing evidence suggests that HES5 is involved in tumor progression across various cancers, including non-small cell lung cancer (NSCLC), breast cancer, neuroblastoma, and hepatocellular carcinoma." (PMID 40128298, 2025). "For instance, the positioning patterns of HES5 and FLI1 are highly indicative of cancer, with both HES5 and FLI1 repositioned in 100% of breast cancers and FLI1 repositioned in 92.9% of prostate cancers, compared to benign tissue controls." (PMID 31681438, 2019). "For instance, HES5 repositions in breast cancer, but not in benign breast disease nor prostate cancer." (PMID 31681438, 2019). "Interestingly, when we analysed existing clinical breast cancer cohort data, we found that the high expression level of HES5, but not HES1 or HEY1 was significantly correlated with a poor brain metastasis-free survival of breast cancer patients." (PMID 23495140, 2013).
glioma (4 papers, 2020). A benign or malignant brain and spinal cord tumor that arises from glial cells (astrocytes, oligodendrocytes, ependymal cells). "Consistently, HES5 has been suggested to exhibit tumor suppressive effects in B-cell acute lymphoblastic leukemia and glioma." (PMID 32055024, 2020). "Despite these findings, RNA‐seq from a Nf1;Tp53CKO mouse model of glioma where the tumors also lack ASCL1 revealed that although some Notch related genes (Dll3, Hes5, Hes6) were decreased, expression of many of the Wnt related genes seemed unaffected by the loss of ASCL1." (PMID 32573857, 2020).
colon cancer (3 papers, 2013 to 2023). "Up-regulation of the Notch signaling effector, Hes-5 is observed in many human cancers and it has been indicated that Hes-5 suppressed the transcription of FBXW7β in colon cancer cells." (PMID 30791487, 2019). "For this reason Flag-HES5 was overexpressed in HCT116 colon cancer cells and ChIP performed using Flag antibody." (PMID 23776410, 2013). "A positive feedback loop consisting of NICD/Hes5/FBXW7 was identified in colon cancer cells, where the negative regulation of FBXW7 by Hes5, particularly its repressive effect on the transcription of FBXW7, is extremely significant." (PMID 36998461, 2023).
prostate carcinoma (3 papers, 2015 to 2019). A carcinoma that arises from epithelial cells of the prostate gland. "Treatment of LNCaP cells with the DNA demethylating agent 5-aza-2′-deoxycytidine caused de-repression of the HES5 gene, consistent with active epigenetic silencing of the HES5 gene in prostate cancer cells." (PMID 25560400, 2015). "To assess the frequency of HES5 hypermethylation in prostate cancer, we performed targeted bisulphite sequencing of the HES5 promoter in a separate cohort of 39 matched tumour and adjacent benign samples." (PMID 25560400, 2015). "Consistent with observations in human tumours, we found that LNCaP prostate cancer cells exhibit hypermethylation of the HES5 promoter, in contrast to HES5 hypomethylation in benign epithelial cells PrEC." (PMID 25560400, 2015). "We also assessed HES5 methylation in an additional prostate cancer patient cohort using publicly available methylation array data (n=304 tumours, n=49 matched normal samples)." (PMID 25560400, 2015). "Treatment of prostate cancer cells with the demethylating agent 5-aza-2′-deoxycytidine increased HES5 expression and downregulated its transcriptional target HES6, consistent with functional silencing of the HES5 gene in prostate cancer." (PMID 25560400, 2015). "Herein, we characterise an epigenetic alteration at the promoter of the related HES5 gene, which has been recently reported in a panel of genes that showed promise as a prostate cancer marker in biopsy samples." (PMID 25560400, 2015). "Despite the early and frequent silencing of HES5 in prostate cancer, we observed variable expression of the HES5 transcriptional target HES6 in prostate tumour samples, prompting us to investigate other factors that may regulate HES6 expression in prostate tumour cells." (PMID 25560400, 2015). "Future studies will need to include overexpression of HES5 in prostate cancer cells to establish the direct consequences on HES6 and AR signalling, as well as the phenotypic consequences of bypassing HES5 silencing." (PMID 25560400, 2015). "In addition, depletion of HES5 in 5-aza-2′-deoxycytidine-treated prostate cancer cells (both ERG-positive and ERG-negative) will allow an assessment of de-repression of the endogenous HES5 locus on gene expression and cellular phenotypes." (PMID 25560400, 2015). "While the functional role of HES5 methylation in prostate tumourigenesis is yet to be determined, we found that demethylation resulted in downregulation of the HES5-target gene HES6, which has recently been shown to drive progression in prostate cancer via the androgen receptor." (PMID 25560400, 2015). "The tumour-specific methylation changes at the HES5 promoter were consistent within and between cases and comparable with the hypermethylation observed at the GSTP1 gene, which is invariably silenced in prostate cancer and has been extensively studied." (PMID 25560400, 2015).
Stroke (3 papers, 2012 to 2021). Sudden impairment of blood flow to a part of the brain due to occlusion or rupture of an artery to the brain. "At 2 weeks, compared with the stroke group, expression of target gene Hes5 mRNA transcripts in the PSD group decreased, but increased after treatment with YNJYP." (PMID 30386260, 2018). "At 2 weeks, levels of Hes5 mRNA transcripts of rats in the PSD group were significantly lower than those in the stroke group (P < 0.01)." (PMID 30386260, 2018). "A possible future strategy might be to check the levels of some SOX6 and HES5 regulators such as miR-219 or miR-338 and their therapeutic potential in stroke." (PMID 23284893, 2012).
viral infection (3 papers, 2013 to 2024). "The ectopic expression of HES5 significantly increased CSCs population after 72 h of viral infection." (PMID 23495140, 2013). "Further study showed that viral infection upregulated the level of HES1 and HES5 mRNA expression and downregulated that of RBP-Jκ." (PMID 39530666, 2024).
adenoma (2 papers, 2017 to 2020). A neoplasm arising from the epithelium. "Notch target genes, Hes1, Hes5, Hey1, and Hey2, were upregulated ≥2-fold in 33%, 31%, 24%, and 32% of CRCs, respectively, whereas in adenomas, they were overexpressed in 22%, 22%, 11%, and 11%, respectively." (PMID 32211044, 2020). "The expression level of Dll1, Dll3, Jagged1, Jagged2, Notch3, and Hes5 was similar in the small intestine adenomas and the normal tissue epithelium." (PMID 28086833, 2017). "The same Notch members and Hes1, instead of Hes5, seemed upregulated in the adenomas (Notch3 only in the large intestine)." (PMID 28086833, 2017).
B-cell acute lymphoblastic leukemia (2 papers, 2013 to 2020). A neoplasm of lymphoblasts committed to the B-cell lineage, typically composed of small to medium-sized blast cells. "Using methylated CpG island amplification (MCA)/DNA promoter microarray, we identified Notch3 and Hes5 as hypermethylated in human B cell acute lymphoblastic leukemia (ALL)." (PMID 23637910, 2013).
cervical carcinoma (2 papers, 2014 to 2016). A carcinoma arising from either the exocervical squamous epithelium or the endocervical glandular epithelium. "Moreover, Hes-1 and Hes-5 are positively associated with various prognostic factors in early-stage cervical carcinoma, suggesting that both Hes-1 and Hes-5 could be useful biomarkers to predict poor prognosis in patients with cervical carcinoma." (PMID 24899581, 2014).
glioblastoma (2 papers, 2015 to 2018). The most malignant astrocytic tumor (WHO grade IV). "HES5 has been shown to increase activation of STAT3 and STAT3 promotes glioblastoma stem cell renewal, and acts synergistically with Nanog to maintain pluripotency of embryonic stem cells." (PMID 30555629, 2018). "We investigated if the mutually exclusive expression of a Notch pathway ligand (JAG1) and target (HES5) consistent with lateral inhibition could be found in primary glioblastoma by examining in greater detail three previously reported, double stained GBM specimens." (PMID 25557173, 2015).
liver cancer (2 papers, 2020 to 2024). An epithelial or non-epithelial malignant neoplasm that arises from the liver. "This was also reflected by heterogeneous induction of the cholangiocyte marker pan-CK and inhibition of HNF4α in our AKT/HES5-liver cancer mouse model." (PMID 32055024, 2020). "Furthermore, the NOTCH target gene HES5 has both pro- and anti-tumorigenic functions in liver cancer proposing a driver gene dependency and it promotes tumorigenesis with its interaction partner AKT." (PMID 32055024, 2020). "We tested whether HES5 might be activated by NOTCH signaling in liver cancer cell lines." (PMID 32055024, 2020).
medulloblastoma (2 papers, 2010 to 2011). A malignant, invasive embryonal neoplasm arising from the cerebellum. "Furthermore, the elevation of Notch2 and Hes5 in Smoothened-induced medulloblastomas suggests that Hh pathway activation interacts with Notch signaling." (PMID 21379383, 2011). "In conclusion, even though Notch signalling is lost in the majority of cells in Ptc1lox/lox;RBP-Jlox/lox;Math1-Cre tumours, as confirmed by loss of Hes5 mRNA, RBP-J deletion does not appear to influence the characteristics of medulloblastoma initiated by Ptc1 deletion in GNPs." (PMID 20950430, 2010).
pulmonary arterial hypertension (2 papers, 2023 to 2025). Pulmonary arterial hypertension (PAH) is a group of diseases characterized by mean pulmonary artery pressure >20 mmHg and elevated pulmonary arterial resistance leading to right heart failure. "pulmonary artery smooth muscle cells from patients with pulmonary arterial hypertension recapitulated Notch3/Hes5 signaling, ER stress and redox changes observed in PH mice." (PMID 37254738, 2023).
schizophrenia (2 papers, 2015 to 2023). A major psychotic disorder characterized by abnormalities in the perception or expression of reality. "Quetiapine ameliorated the schizophrenia-like behaviors and decreased expression of myelin basic protein and inhibition of Notch signaling molecules, such as Notch1, Hes1, and Hes5, in the forebrain that induced by cuprizone." (PMID 26232790, 2015).
Alzheimer disease (1 paper, 2015). A progressive, neurodegenerative disease characterized by loss of function and death of nerve cells in several areas of the brain leading to loss of cognitive function such as memory and language. "For example, we found that SPON1 and RRAS2, overrepresented specifically in L-RG HES5+ cells and thus may relate to gliogenesis, contain SNPs associated with Alzheimer’s disease (P=2.07E−4, Odds=15.26)." (PMID 25799239, 2015).
anaplastic thyroid carcinoma (1 paper, 2025). "Notch1 inhibition through Hes5 has been reported to significantly suppress cell migration and EMT in anaplastic thyroid carcinoma." (PMID 41315239, 2025).
angiomyolipoma (1 paper, 2017). A neoplasm with perivascular epithelioid cell differentiation often associated with tuberous sclerosis. "WB and qPCR confirmed that N1ICD, Rheb, and Notch target gene HES5 were reduced in angiomyolipoma cells in N-medium." (PMID 29184052, 2017).
brain tumor (1 paper, 2018). "HES5 mRNA was found high expression in brain tumor tissue and in fetal heart, but it has not reported for gastric cancer." (PMID 30212456, 2018).
cerebral infarct (1 paper, 2012). "NOG gene (Noggin), was downregulated in the PI area at 3 d and HES5, involved in neurogenesis, was downregulated in both the core and PI areas at 24 h but only in the core of the lesion at 3 d after cerebral infarct." (PMID 23284893, 2012).
colorectal adenoma (1 paper, 2020). An adenoma that arises from the colon or rectum. "We investigated mRNA expression of four Notch receptors (Notch1–4), five ligands (Jag1, Jag2, Dll1, Dll3, and Dll4), and four target genes (Hes1, Hes5, Hey1, and Hey2) using highly specific TaqMan gene expression assays in colorectal adenomas and cancers." (PMID 32211044, 2020).
colorectal tumours (1 paper, 2013). "Thus FBW7 heterozygosity results in increased Hes5 expression both in human colorectal tumours and in the APCmin;Fbw7ΔG/+ mouse model, suggesting that the NICD/HES5/FBW7β positive feedback loop is the molecular mechanism that underlies FBW7 haploinsufficiency in tumour suppression." (PMID 23776410, 2013).
diabetic retinopathy (1 paper, 2017). "In this study, we found that CpG methylation regulates pathways that are used as pharmacological targets in diabetic retinopathy progression, such as angiogenesis (ETS1, HES5, PRDM16)." (PMID 28924151, 2017).
glomerulonephritis (1 paper, 2021). A renal disorder characterized by damage in the glomeruli. "Several HES5 targeting reagents, including neutralizing antibody and receptor antagonists, are currently available and proven effective in the intervention of glomerulonephritis and Sjögren’s syndrome." (PMID 34689159, 2021).
intracerebral hemorrhage (1 paper, 2022). A cerebrovascular disorder characterized by bleeding into one or both cerebral hemispheres including the basal ganglia and the cerebral cortex. "The Hes5 was reported to be downregulated after brain injury, while the Mmp12 expression was significantly increased in intracerebral hemorrhage." (PMID 35501920, 2022).